HLA-F-AS1 (HLA-F antisense RNA 1)
Gene: Long non-coding RNA gene on chromosome 6 (29,707,518 to 29,828,496, reverse strand). Ensembl gene ENSG00000214922.
Diseases named in the same sentence as HLA-F-AS1 in open-access papers:
HLA-F-AS1 is named in the same sentence as 4 diseases in open-access papers, as found by Europe PMC text mining. Sharing a sentence is not in itself a finding about the gene and the disease. The quoted sentences say what the papers report.
polycystic ovary syndrome (2 papers, 2022 to 2025). A disorder that manifests as multiple cysts on the ovaries. "HLA-F-AS1, a long non-coding RNA (lnRNA), is found to be upregulated in polycystic ovary syndrome." (PMID 41300831, 2025).
colorectal cancer (1 paper, 2022). A primary or metastatic malignant neoplasm that affects the colon or rectum. "For example, HLA-F-AS1 expression has been shown to influence the production and migration of macrophages via intermediates such as microRNA (miRNA) and profilin 1 in colorectal cancer." (PMID 35935961, 2022).
Crohn disease (1 paper, 2024). A gastrointestinal disorder characterized by chronic inflammation involving all layers of the intestinal wall, noncaseating granulomas affecting the intestinal wall and regional lymph nodes, and transmural fibrosis. "Some of these traits (i.e., platelet-to-lymphocyte ratio, general cognitive ability) as well as Crohn’s disease are further linked to JIA through the neighbouring cluster 6 genes (HLA-FAS1, BAK1, CLN3, SGF29)." (PMID 39175752, 2024).
cancer (1 paper, 2022). A tumor composed of atypical neoplastic, often pleomorphic cells that invade other tissues. "HLA-F antisense RNA 1 (HLA-F-AS1) is a lncRNA that participates in several cancers by increasing cancer cell proliferation and movement to accelerate cancer progression." (PMID 35603775, 2022).